MPO (myeloperoxidase)
Diseases named in the same sentence as MPO in open-access papers (continued):
Sharing a sentence is not in itself a finding about the gene and the disease.
colitis (continued). "The activities of MPO, SOD and GSH-Px, and the levels of MDA and GSH in colonic tissues could reflect quantitatively the colitis of mice, while assisting in speculating the pathogenesis of the TNBS-induced colitis and the action mechanism of drugs." (PMID 35541446, 2018). "Meanwhile, the oxidative stress indicated by myeloperoxidase (MPO), reduced glutathione (GSH), malondialdehyde (MDA), and serum nitrate (NO) concentrations was higher in mice with DSS-induced colitis than in the control group mice, but dietary Q or Q+MQ supplementation counteracted this trend." (PMID 30539022, 2018). "In a colitis mouse model, intra-rectal injections with CST resulted in decreased serum levels of the acute phase reactant C-reactive protein (CRP) and suppressed activity of myeloperoxidase (MPO), which is a marker for granulocyte infiltration." (PMID 30337922, 2018). "Oral administration of bergenin (50 mg/kg), 5-ASA (100 mg/kg) and rosiglitazone (20 mg/kg) significantly improved disease symptoms of mice with colitis, including reducing DAI score and MPO activity, rescuing the shortening of colon length, and alleviating histopathological changes in colons." (PMID 29375382, 2017). "In animals with the intact pituitary gland, a 3-fold increase in myeloperoxidase activity was observed in the colonic mucosa in comparison to a value observed in control pituitary-intact animals without colitis." (PMID 28538694, 2017). "This observed association between VEGF production and leukocytic infiltration in inflamed colonic tissues was consistent with the present findings, where colitis induction resulted in increased VEGF level and MPO activity indicating pathologic angiogenesis and increased neutrophilic infiltration." (PMID 28769047, 2017). "MPO activity, the TNF-α level, and the IL-1β level in the colitis rats were significantly higher than those in the control rats, and these effects were attenuated by acupuncture treatments at a neurogenic spot (Neuro-Sp), but not by stimulation of a nearby non-neurogenic site (Nearby site)." (PMID 29123119, 2017). "In hypophysectomized rats, administration of ghrelin failed to affect the colitis-evoked increase in mucosal levels of interleukin-1β and myeloperoxidase." (PMID 28538694, 2017). "In animals without colitis, removal of the pituitary gland resulted in a significant 32% increase in the myeloperoxidase activity in the colonic mucosa." (PMID 28538694, 2017). "Six-day intraperitoneal administration of ghrelin did not affect myeloperoxidase activity in the colonic mucosa in pituitary-intact rats without induced colitis." (PMID 28538694, 2017). "Treatment with ghrelin was without any significant effect on myeloperoxidase activity in colonic mucosa in hypophysectomized rats with colitis." (PMID 28538694, 2017). "The study in the TNBS-induced rat colitis by Mochizuki and Hasegawa showed that EGCG could significantly decrease the enzyme MPO and histamine in the distal gut mucosa." (PMID 28335502, 2017). "On the contrary, the level of MPO activity in the ileum from the colitis rats was not different (p>0.05) as compared to that of the ileum from the non colitis controls [open bars]." (PMID 28493993, 2017). "MPO levels in the groups treated with 300 and 600 mg/kg extract significantly decreased compared to those in the TNBS-only group whereas treatment with the extract at 150 mg/kg did not affect the MPO levels in mice with TNBS-induced colitis." (PMID 28946886, 2017). "Our results showed that oral administration of bergenin remarkably alleviated disease symptoms of mice with dextran sulfate sodium (DSS)-induced colitis, evidenced by reduced DAI scores, shortening of colon length, MPO activity and pathologic abnormalities in colons." (PMID 29375382, 2017). "On the other hand, obestatin failed to affect mucosal IL-1β concentration and MPO activity in the colon of rats without induction of colitis." (PMID 26798415, 2016).
colitis (continued). "Administration of Mutaflor or rifaximin given alone as well as treatment with the combination of rifaximin plus Mutaflor was without any significant effect on mucosal myeloperoxidase activity in the colon in the rats without colitis induction." (PMID 27433160, 2016). "Clinical signs of colitis and colonic histopathological parameters were evaluated, along with the determination of levels of reduced glutathione and lipid hydroperoxide (LOOH), the superoxide dismutase (SOD), and myeloperoxidase (MPO) activity in colon." (PMID 27847525, 2016). "Administration of obestatin for 7 or 14 days was without effect on mucosal myeloperoxidase activity in the colon in the rats without colitis induction." (PMID 26798415, 2016). "In contrast to that, mucosal activity of MPO in the colon of rats without colitis was low and administration of obestatin was without effect on colonic MPO activity in those rats." (PMID 26798415, 2016). "In DSS-induced colitis mice, LL202 decreased MPO and iNOS activities, which suggested that LL202 could reverse the infiltration of inflammatory cells into colon tissues." (PMID 27590510, 2016). "Intraperitoneal administration of ghrelin for six or 13 days did not affect mucosal myeloperoxidase activity in the colon in rats without colitis induction." (PMID 27598133, 2016). "Moreover, we selective activated A3AR and found that administration of the A3AR agonist 2-Cl-IB-MECA alleviated the clinical symptoms and MPO activity and reduced tissue injury of DSS-induced murine colitis." (PMID 25762375, 2015). "Increase in MPO was also detected in water-treated parental bHMA mice, but no histological signs of colitis were observed in any group of water-treated HMA mice." (PMID 26697117, 2015). "In the interpretation of WAS/DSS interactions it need be emphasized that WAS failed to alter the severity of DSS-induced colitis as judged by body weight, colon length, colon weight, colonic MPO content, and disease activity score." (PMID 26217204, 2015). "Treatment with 5-ASA or 1,25(OH)D3 ameliorated colitis by lowering CMDI (P = 0.049, P = 0.040, respectively), histological colonic damage score (P = 0.010, P = 0.005, respectively), and MPO activity (P = 0.0003, P = 0.0013, respectively) compared with the TNBS group." (PMID 26718757, 2015). "In this study, MPO activity in reserpine (RSP, 6 mg/kg) group as well as control group was markedly elevated showing that neutrophil infiltration to the inflamed tissue is increased following induction of colitis." (PMID 27355055, 2014). "CONTROL mice showed no clinical or colonoscopic signs of colitis, no macroscopic or microscopic damage and had low colonic MPO activity." (PMID 25313594, 2014). "The i.p. administration of CB 13 (0.1 mg/kg) once daily 15 min before and for 3 days after induction of colitis did not influence the macroscopic damage score, MPO activity or ulcer score." (PMID 25275313, 2014). "In contrast, repeated WAS did not modify colon length, colonic myeloperoxidase content and circulating proinflammatory cytokines, parameters used to assess colitis severity." (PMID 25414650, 2014). "To investigate the effects of ERCs on attenuation of inflammatory cell infiltration in the colitis mice, we have detected and compared intra-colon MPO (a biomarker for activated neutrophils) and Mac-1 positive cell infiltration in both untreated and ERC-treated colitis mice." (PMID 25475342, 2014). "Compared with the TNBS model group, the DAI scoring, plasma and colonic mucosa Hcy levels, MPO activity and contents of MDA, IL-1β, IL-6, TNF-α, MMP-2, MMP-9 in colon and EB in small intestine were significantly increased in the TNBS-induced colitis rats with simultaneous Hcy injection (P < 0.01)." (PMID 24787389, 2014).
colitis (continued). "In this study, the body weights of rats with colitis were significantly decreased and exhibited different degrees of fecal blood with increased DAI and HI scoring and elevated MPO activity, suggesting that a rat colitis model had been successfully established, induced by TNBS/ethanol." (PMID 24787389, 2014). "In this study, the DAI and HI scores, MPO activity in colonic tissues, as well as the MDA, TNF-α, IL-1β, and IL-6 levels, were simultaneously increased in TNBS-induced colitis rats with Hcy injection, indicating that Hcy can aggravate the oxidative and inflammatory damage in rats with colitis." (PMID 24787389, 2014). "EE aggravated experimentally induced colitis, but not gastritis, as shown by an increase in the disease activity score and the colonic myeloperoxidase content." (PMID 23349972, 2013). "However, our study found that increased MDA level and MPO activity and reduced SOD activity in colonic tissue of DSS-colitis group were significantly improved after oral administration of picroliv accompanying with the amelioration of inflammation." (PMID 23125487, 2012). "While there was some variability in MPO levels of WT mice, all 20 mice were within 5 standard deviations (SD) of the mean in accord with lack of evidence of colitis by histology." (PMID 22957064, 2012). "Regarding the inflammatory parameters analyzed in our studies, 15d-PGJ2 administration inhibits MMP-9, iNOS and COX-2 expression, MPO activity and MDA accumulation in inflammation-related pathologies such as restraint stress exposure, cerebral ischaemia, and colonic inflammation and dysfunction." (PMID 20929574, 2010). "It was investigated whether dietary polyunsaturated fatty acids (PUFA) could influence colonic injury, tissue DNA damage, cytokines and myeloperoxidase activity (MPO) and plasma corticosterone in DSS-induced colitis rats." (PMID 20615224, 2010). "Furthermore, our results revealed an enhancement in local MPO activity in all rBanLec-pretreated groups compared to the PC group (experimental colitis without rBanLec treatment)." (PMID 40305159, 2025). "In murine models of colitis induced by dextran sulfate sodium (DSS), baicalein treatment markedly lowers colonic levels of these cytokines, reduces neutrophil infiltration (as evidenced by decreased myeloperoxidase (MPO) activity), and improves histological damage scores." (PMID 41451362, 2025). "The acute colitis mice with 3% DSS administration presented with reduced body size, with pale skin, lusterless hairs, and the presence of hemorrhages in the intestinal tract, MPO staining revealed peripheral neutrophil infiltration particularly in the colitis tissues." (PMID 40691131, 2025). "This current study was the first to highlight the spatial co-localisation of 3 essential NETosis enzymes: MPO, NE and citH3 in the colon tissue using multi-plex IF imaging, further reinforcing the involvement of NETs during the pathogenesis of DSS-induced experimental colitis." (PMID 40459411, 2025). "Furthermore, Fuzhuan tea crude extract significantly decreased TNF-α, IL-1β and IFN-γ inflammatory cytokines’ levels, and significantly reduced myeloperoxidase activity, nitric oxide, and malondialdehyde levels in colon tissue, thus improving DSS-induced colitis in mice." (PMID 39272608, 2024). "Conversely, in a mouse model of colitis, Pingyin rose essential oil (PREO) was found to enhance the enzymatic activities of SOD and catalase (CAT), while reducing NO, malondialdehyde (MDA) and myeloperoxidase (MPO) production and restoring intestinal barrier integrity." (PMID 39360286, 2024). "Overall, the absence of MPO did not affect DSS colitis clinical outcomes." (PMID 38673843, 2024). "It was observed that colitis did not interfere with the requirement of MPO activity and TNF-α levels, indicating that these inflammatory markers were not activated or deactivated and that other cytokines not investigated (IL-6 and IL-1β, e.g.)may be involved." (PMID 37577725, 2023).
colitis (continued). "In addition, healthy donor (HD) bacteria significantly reduced the levels of inflammatory markers Myeloperoxidase (MPO) and Eosinophil peroxidase (EPO), and various pro-inflammatory factors, in colitis mice, and increased the secretion of the anti-inflammatory factor IL-10." (PMID 35237276, 2022). "Meanwhile, when comparing the colitis + melatonin (5 mg/kg) group to the colitis group without treatment, a significant decline in MPO (P < 0.0001) (− 26.44%) and MDA (P < 0.001) (− 36.38%) levels, as well as a significant increase (P < 0.001) (+ 63.78%) in GSH levels, were noted." (PMID 35428860, 2022). "However, UroA treatment failed to block the increased MPO levels in Cyp1a1-/- mice that were subjected DSS-induced colitis model." (PMID 36159798, 2022). "Our results showed that treatment with ligands of MOR and FFAR separately and in combination may affect immune function in the inflammation seen by altering MPO activity even though these ligands had no significant influence on the severity of colitis." (PMID 34833919, 2021). "After three cycles of DSS administration, mice with colitis showed reduced colon length (a marker of intestinal inflammation) as well as increased levels of DAI, MDA (a measure of the colonic oxidative insult), MPO (an index of neutrophil accumulation), and inflammatory factors (IL-1β and IL-6)." (PMID 34393786, 2021). "MPO activity (representing neutrophil infiltration in colonic mucosa) elevated by colitis was decreased by TRL to a level close to that of the normal group, and chemical reduction of TRL or co-treatment with ZnPP partly undermined the ability of TRL to decrease MPO activity." (PMID 34832874, 2021). "Interestingly, administration of S. boulardii greatly reduced the activity of MPO and inhibited the expression of those cytokines in DSS-induced colitis mice, indicating that the protective effect of S. boulardii against colonic damage is associated with the regulation of inflammatory cytokines." (PMID 34367460, 2021). "Furthermore, vagotomy did not affect Paenalcaligenes hominis-induced colitis; specifically, it did not inhibit colon shortening, myeloperoxidase activity, and IL-1β expression or alter NF-κB+/CD11c+ cell populations." (PMID 32669127, 2020). "In the present study, however, we found that the TRPA1 antagonist HC-030031 as well as genetic deletion of TRPA1 failed to significantly alter the severity of DSS-induced colitis as judged by body weight, colon length, colon weight, colonic MPO activity and disease activity score." (PMID 32451393, 2020). "Although the control (PBS-treated) IL-10 KO mice used here did not develop severe colitis, they did display short colons, and low but detectable level of colon MPO activity, both suggestive of chronic inflammation, which was attenuated by flagellin immunization." (PMID 31827095, 2019). "Treatment with UroA/UAS03 significantly protected from DSS-induced colitis as evident from decreased gut permeability, reduced shortening of colons, increased colon weight/length ratio, reduced inflammation (serum IL-6, IL-1β, TNF-α as well as colonic tissue MPO levels)." (PMID 30626868, 2019). "Our findings revealed that increased MPO activity induced by TNBS could be weakened after administration of AZ-SFE at test doses, showing the protective effect of AZ-SFE against tissue injury in experimental colitis." (PMID 31387229, 2019). "The severity of colitis in mice was quantitatively reflected by the levels of MDA and GSH, and the activities of MPO, GSH-Px and SOD in colonic tissues, besides, these indicators could also help predict the pathogenesis of experimental colitis and the action mechanism of drugs." (PMID 32133064, 2019). "Moreover, the observation that obestatin did not affect mucosal IL-1β concentration, and MPO activity in the colon of rats without induced colitis suggested that obestatin did not disturb the immune system when no signs of inflammation were present." (PMID 29865176, 2018).
colitis (continued). "In the mouse model, oral administration of KM1608 significantly improved DSS-induced colitis symptoms, such as disease activity index (DAI), colon length, and colon weight, as well as suppressed the expression of IL-6, TNF-α, and myeloperoxidase (MPO) in the DSS-induced colitis tissues." (PMID 30126158, 2018). "In another experiment regarding the effect of EC on TNBS-induced colitis rat models, EC could not decrease the neutrophil infiltration through any change in the enzyme MPO." (PMID 28335502, 2017). "Melatonin significantly attenuated colitis in mice, as indicated by the macroscopic score (1.90 ± 0.34 vs. 3.82 ± 0.62 for melatonin- and TNBS-treated mice, respectively), ulcer score (0.87 ± 0.18 vs. 1.31 ± 0.19, respectively), and MPO activity (4.68 ± 0.70 vs.6.26 ± 0.94, respectively)." (PMID 26899972, 2016). "In addition to the clinical and histological severity, the level of MPO activity, as a parameter of neutrophil accumulation, was marginally detectable in the absence of DSS induction, but was increased in colons of mice with DSS-induced colitis." (PMID 25762375, 2015). "As compared with Group C, the DAI, HI scores, MPO activity, and MDA content were significantly increased in Group D (P < 0.01), suggesting that Hcy may aggravate oxidative and inflammatory injury in rats with TNBS-induced colitis." (PMID 24787389, 2014). "EE failed to modify IAA-induced gastritis as judged from its lack of effect on DAS and gastric MPO content, whereas the susceptibility to DSS-evoked colitis was enhanced by enriched housing as deduced from an increase in weight loss, DAS and colonic MPO content." (PMID 23349972, 2013). "However, the effects of FSG treatment on MDS, MD and MPO activity did not reflect a total inhibition since values obtained for these parameters remained higher than in rats without colitis." (PMID 23166707, 2012). "Mice with colitis induced by DSS exhibited disruption of the epithelial barrier, a marked decrease in the number of crypts, and marked infiltration of inflammatory cells, predominantly neutrophils, into the mucosa and sub mucosa of the colon, corroborating the MPO assay." (PMID 22073270, 2011). "Furthermore, the effect of protective construction disappeared and the expression of colonic MPO, IL-1β, IL-6, or TNF-α at the protein level was not counteracted by BD in PGF mice, indicating that the gut microbiota was essential for the effect of BD during colitis." (PMID 40745657, 2025). "Interestingly, the damage associated with colitis resulted in a significant elevation of serum levels of CRP and MPO activity in the colon, while these elevated levels were notably reduced in those rats that received MSPNP treatment, which exerted their protective role against colon damage." (PMID 35745756, 2022). "In addition, the results from MPO determination also showed that supplementation of QCWZD significantly decreased MPO activity, an indicator of mucosal neutrophil infiltration, in the colonic mucosa during the recovery phase of acute colitis compared with that of mice with DSS treatment alone." (PMID 34557102, 2021). "Pathological severity of colitis, however, was significantly reduced in the group of mice treated with AES as characterized by reduced body weight loss, alleviated clinical manifestations (DAI), decreased histological score and MPO activity as compared to mice without AES treatment." (PMID 33117347, 2020). "Weight loss, colon weight/colon length ratio, spleen weight and colonic MPO activity, was not statistically different between DSS-treated WT and PepT1−/− mice, suggesting that physical separation at weaning was not sufficient to affect the host susceptibility to colitis." (PMID 32694535, 2020).